ICAM1 (intercellular adhesion molecule 1)
Diseases named in the same sentence as ICAM1 in open-access papers (continued):
Sharing a sentence is not in itself a finding about the gene and the disease.
Sepsis (continued). "Thus, our present study was performed firstly to confirm the effect of ICAM-1 on polymicrobial sepsis and secondly to detect the apoptotic rate and expression levels of costimulatory molecules in thymus and spleen to clarify the effect of ICAM-1 on status of immune cells." (PMID 24891762, 2014). "However, the direct role of ICAM-1 in polymicrobial sepsis remained controversial." (PMID 24891762, 2014). "In conclusion, ICAM-1 blockade may improve outcome of sepsis." (PMID 24891762, 2014). "In our study, 6 key target genes involved in sepsis and COVID-19 treatment with JHD were identified including AKT1, MMP9, ICAM1, TLR4, BCL2 and HIF1A based on PPI network." (PMID 41411324, 2025). "The gene differential expression analysis showed that compared with the healthy group, the sepsis patient group exhibited significantly lower expression levels of AKT1 and BCL2, but significantly higher expression levels of MMP9, ICAM1, TLR4, and HIF1A." (PMID 41411324, 2025). "The activity of myeloperoxidase and the concentration of ICAM1 and VCAM1 in the liver and lungs, as well as the expression of ICAM1 and VCAM1 on vascular endothelial cells in these tissues, increased in mice with CLP surgery-induced sepsis." (PMID 38928206, 2024). "This study aimed to explore the effects of Kupffer cell inactivation on ICAM-1 and VCAM-1 expression in liver and lung endothelial cells in mice following CLP-induced sepsis." (PMID 38254684, 2024). "Pro-inflammatory cytokines, mainly TNF-α, upregulate the expression of both ICAM-1 and VCAM-1, and these adhesion molecules are highly expressed in endothelial cells during sepsis." (PMID 38254684, 2024). "Serum levels of adhesion molecules, including E-selectin, P-selectin, intercellular adhesion molecule-1 (ICAM-1), and vascular cell adhesion molecule-1 (VCAM-1), have been observed to correlate with sepsis severity, number of organ failures, and mortality." (PMID 39063011, 2024). "In the liver, pretreatment with GdCl3 resulted in reduced protein expression of ICAM-1 and its immunoreactivity, which co-localized with LYVE-1 expression in mice with sepsis." (PMID 38254684, 2024). "We also investigated the expression levels of ICAM-1 and VCAM-1 proteins in lung tissue and their immunoreactivity in structures localized with CD31 expression in GdCl3-pretreated mice with CLP-induced sepsis." (PMID 38254684, 2024). "This suggested there was increased expression of ICAM-1 and VCAM-1 predominantly on liver sinusoidal endothelial cells and pulmonary endothelial cells, respectively, during sepsis." (PMID 37686458, 2023). "Interestingly, ICAM1 (intercellular adhesion molecule 1) was found in GWAS studies for both sepsis and COVID-19 and was also a persistently upregulated gene only in non-survivors, suggesting persistent dysregulation of this gene may be involved in worse outcomes for both diseases." (PMID 37822940, 2023). "The intraperitoneal injection of PRE-084 mitigated sepsis-induced ALI, as evidenced by a decrease in ICAM-1, IL-6 levels, lung PMN infiltration, and lung vascular leakage." (PMID 38201208, 2023). "Our study showed increased ICAM-1 and VCAM-1 immunoreactivity in co-localization with LYVE-1 in a sepsis model." (PMID 37686458, 2023). "Our study suggests that the glycosaminoglycan heparan sulfate and the glycoproteins ICAM-1, VCAM-1, and E-selectin are significantly increased in the plasma of sepsis patients with cognitive impairment." (PMID 36802387, 2023). "MiR-15b-5p notably supports or opposes endothelial migration and proliferation, in both physiological conditions and altered environments as sepsis, by targeting the protein kinase B3 (AKT3) and ICAM1/ focal adhesion kinase (FAK) pathways, respectively." (PMID 37587410, 2023). "In contrast, other research has reported that the ICAM-1 and VCAM-1 levels correlated significantly with organ dysfunction and mortality in patients with sepsis." (PMID 36333626, 2023).
Sepsis (continued). "As sepsis advances, VCAM-1 and ICAM-1, which are expressed in large quantities on the activated EC surface of septic patients, are also cleaved and released into the circulation." (PMID 38259971, 2023). "Under sepsis condition, differentially overexpressed CNTLN, ICAM1, and PLAGL1 in PTB were consistently observed." (PMID 36788602, 2023). "Adhered PBMCs and PMNs were significantly increased in sepsis serum mixed medium compared to the control, similar to the mRNA and protein levels of VCAM-1 and ICAM-1." (PMID 35145983, 2022). "Compared with the sepsis serum group, the mRNA levels of VCAM-1 (1.00 ± 0.03 vs. 0.36 ± 0.01, p < 0.05) and ICAM-1 (1.00 ± 0.06 vs. 0.37 ± 0.01, p < 0.05) were significantly reduced after treatment with M8I." (PMID 35145983, 2022). "Our results indicated that sepsis serum promoted the adhesion of leukocytes to HUVECs by improving the expression of VCAM-1 and ICAM-1." (PMID 35145983, 2022). "The AUCs of Urokinase, ICAM-1, and VEGFR2 and the combination for the diagnosis of sepsis were 0.650, 0.688, 0.643, and 0.741, respectively." (PMID 35363162, 2022). "Resistin was also reported to be associated with endothelial cell adhesion molecules, including intercellular adhesion molecule 1 (ICAM-1) and vascular cell adhesion molecule-1 (VCAM-1), in sepsis." (PMID 35784283, 2022). "As we commented above, we observed both lower TNFα concentration in brain and expression of ICAM-1 in circulating PMN and pial vessels of mice with sepsis previously treated with cit-AuNP." (PMID 33608025, 2021). "In patients on IMV, the best predictive model for extrapulmonary sepsis included SOFA score, IL-18, and IL-1RA (log-rank P = 0.002), whereas for pulmonary sepsis included PaO2/FiO2, ICAM-1 and IL-1RA (log-rank P = 0.0002)." (PMID 34811434, 2021). "ICAM-1 and L-selectin were measured in circulating polymorphonuclear (PMN) leukocytes 6 h after induction of sepsis in mice." (PMID 33608025, 2021). "For example, genes related to leukocyte adhesion to EC, such as Selp (P-selectin), Icam1 (intercellular adhesion molecule 1), were significantly upregulated in PCV during sepsis." (PMID 34638535, 2021). "It was demonstrated ICAM-1 activation in neutrophils triggers neutrophil extracellular traps (NET) formation and then results in exaggerated sepsis-induced inflammation." (PMID 33608025, 2021). "Increased expression of ICAM-1 and VCAM-1 facilities the recruitment of macrophages and neutrophils into the myocardium, leading to inflammatory response in sepsis." (PMID 32411123, 2020). "Increased expression of adhesion molecules, such as ICAM-1 and VCAM-1, has been shown to recruit neutrophils and macrophages into the myocardium, leading to cardiac dysfunction in sepsis." (PMID 32411123, 2020). "Expression of IL6, ICAM1, and VCAM1 were significantly upregulated following treatment of the HMECs with LPS for 24 h confirming induction of sepsis." (PMID 31231228, 2019). "Our results were further validated in an in vivo model of sub-lethal LPS-induced sepsis, whereby siRNA mediated knockdown of UCA1 and HULC lncRNAs prevented induction of VCAM1, ICAM1, and IL6, as assayed by immunohistochemistry." (PMID 31231228, 2019). "Taken together, these results indicate that increase in proinflammatory ICAM1, VCAM1, and IL6 in HMECs during LPS induced sepsis in vitro is at least in part due to increase in expression of the lncRNAs HULC and UCA1." (PMID 31231228, 2019). "The expression of VCAM-1, ICAM-1, E-selectin and L-selectin by CD34+/CD133+-stem cells was significantly upregulated in septic patients, and correlated with sepsis severity." (PMID 29601599, 2018). "Carbon monoxide released from tricarbonyldichlororuthenium-(II)-dimers attenuated hepatic accumulation of PMN, expression of the Intercellular Adhesion Molecule 1 (ICAM-1) and activation of NF-κB in murine polymicrobial sepsis." (PMID 28241480, 2017).
Sepsis (continued). "We also show that the small intestinal E-selectin and ICAM-1 expressions increased in SIRT2KO and decreased in SIRT2KI mice versus those in WT sepsis mice." (PMID 28503576, 2017). "Next, we assessed the ICAM-1 expression in small intestinal tissue in WT, SIRT2KO, and SIRT2KI mice with sepsis." (PMID 28503576, 2017). "The mRNA expression of ICAM-1 and VCAM-1 in liver and lung were remarkably elevated after burn sepsis." (PMID 26550025, 2015). "Our data elucidate the late inflammatory changes in plasma during the first 24 hours of severe sepsis diagnosis in ICU patients, and demonstrate inflammation-induced PMN adhesion to hCMEC/D3, mediated by β2-integrin-ICAM-1 interaction." (PMID 25882865, 2015). "Inflammatory mediators and cell adhesion molecules including ICAM-1, VCAM-1, P-selectin, and E-selectin participate in inflammatory sepsis induced lung injury." (PMID 25120287, 2014). "However, overexpression of ICAM-1 on endothelial cells from nonspecific organs may be a leading cause of sepsis-induced organ dysfunction." (PMID 24891762, 2014). "In a polymicrobial sepsis model, HES inhibited the inflammatory cytokine response, neutrophil infiltration and expression of intercellular adhesion molecule-1 (ICAM-1) mRNA." (PMID 17697359, 2007). "However, in sepsis, HES balanced induced substantial hepatic cytokine expression (e.g., a 512-fold increase in ICAM-1), highlighting a potential for hepatotoxicity in inflammatory states." (PMID 41012713, 2025). "The expression of ICAM-1 on neutrophils can increase inducible nitric oxide synthase (iNOS) production and neutrophil extracellular trap (NET) formation, potentially exacerbating inflammatory responses and tissue damage during sepsis." (PMID 41252417, 2025). "By inhibiting the expression of ICAM-1/VCAM-1 and suppressing the phosphorylation and internalization of VE-cadherin, 4-OI effectively reduces leukocyte adhesion and vascular leakage, which are critical factors in sepsis-induced organ injury." (PMID 40524158, 2025). "Nevertheless, other hub genes such as ICAM1, CTSD, SNX3, and SLC22A4 also demonstrated biological relevance in sepsis and may contribute to disease pathogenesis through complementary mechanisms." (PMID 41445732, 2025). "As a response, this also increases the expression of cell-adhesion molecules, such as intercellular adhesion molecule-1 (ICAM-1) and vascular cell adhesion molecule-1 (VCAM-1), where the levels of cell-adhesion molecules directly correlate with sepsis severity and organ dysfunction." (PMID 41374401, 2025). "Similarly, Kupffer cells from rats with CLP-induced sepsis had a significant increase in the concentration of TNF-α, accompanied by an increase in ICAM-1 mRNA levels in the whole-liver tissue." (PMID 38254684, 2024). "Our findings indicate that SP upregulates the expression of ICAM1 and VCAM1 on vascular endothelial cells in the liver and lungs, thereby increasing leukocyte infiltration in these tissues of mice with CLP surgery-induced sepsis by activating NK1R." (PMID 38928206, 2024). "The details of the cell types and molecular pathways in which ICAM-1 participates to enhance inflammation in sepsis are not yet fully elucidated but are emerging." (PMID 37237555, 2023). "In sepsis, endothelial cells express inflammatory cell-related adhesion molecules such as P-selectin, E-selectin, vascular cell adhesion molecule 1 (VCAM1), and intercellular adhesion molecule 1 (ICAM1)." (PMID 36769749, 2023). "Furthermore, PKCδ inhibition was lung protective and decreased sepsis-induced VCAM-1 and ICAM-1 endothelial expression." (PMID 38259971, 2023). "For instance, our findings suggest that decreased levels of certain cytokines, such as ICAM-1, may be indicative of zone 1 ROP, sepsis, and RDS." (PMID 38259597, 2023).
Sepsis (continued). "Meta-analysis of biomarkers ICAM-1 (SMD 0.41; 95% CI 0.05–0.76; p = 0.03; I2 = 50%) and VCAM-1 (SMD 0.55; 95% CI 0.12–0.98; p = 0.01; I2 = 82%) revealed higher pooled mean concentration in patients with SAE compared to the patients with sepsis alone." (PMID 36802387, 2023). "Moreover, the use of antibody blocking these molecules such as anti-Intercellular adhesion molecule-1 (ICAM-1) and vascular adhesion molecule-1 (VCAM-1) showed to prevent myocardial neutrophil accumulation and cardiac dysfunction in animal models of sepsis." (PMID 36139408, 2022). "The sepsis model mice revealed a significant increase in hepatic ICAM-1 expression compared with the control, while the mice under NM treatment exhibited significant downregulation of LPS-induced endothelial ICAM-1 expression." (PMID 35345558, 2022). "Urokinase, ICAM-1, and VEGFR2 were significantly different between sepsis group and SIRS group." (PMID 35363162, 2022). "Urivariate analysis of cytokines, Urokinase, ICAM-1, VEGF-C for predict sepsis." (PMID 35363162, 2022). "As NETs and iNOS were previously shown to be deleterious in sepsis, hence, CIRP‐induced NET/iNOS‐forming ICAM‐1+ neutrophils could exaggerate inflammation and injury to the lung during sepsis." (PMID 34953031, 2022). "Multiple factor analysis of Urokinase, ICAM-1, VEGFR2 for predict sepsis adjusted by age and sex." (PMID 35363162, 2022). "On the contrary, platelet microparticles containing miR-223 reduce intercellular adhesion molecule 1 (ICAM-1) expression and binding to peripheral blood mononuclear cells by endothelial cells, providing a possible protective role against excessive sepsis-induced vascular inflammation." (PMID 35990654, 2022). "However, the MMP8 inhibitor suppressed the leukocyte adhesion promoted by sepsis serum by decreasing the expression of VCAM-1, ICAM-1, p-p38, and p-ERK1/2." (PMID 35145983, 2022). "When analyzing patients on IMV, the best predictive model for extrapulmonary sepsis included APACHE II score, IL-18, Ang-2 and IL-1RA (AUC: 0.835, 95%CI: 0.716–0.954), and for pulmonary sepsis included APACHE II score, Ang-2 and ICAM-1 (AUC: 0.784, 95%CI: 0.666–0.902)." (PMID 34811434, 2021). "Sepsis increased ICAM-1, but not L-selectin, expression in circulating PMN leukocytes compared to the sham group." (PMID 33608025, 2021). "Phenotypes were validated in an independent replication cohort (N = 86) with greater sepsis severity, which similarly demonstrated lower HDL-C, ApoA-I, and higher ICAM-1 in the Hypolipoprotein cluster and worse outcomes (46% rapid recovery, 23% CCI, 31% early death; 28-day mortality, 42%)." (PMID 34535154, 2021). "Cit-AuNP treatment performed 2 h after induction of sepsis reduced the ICAM-1 and did not change de L-selectin expression in PMN leukocytes compared to saline-treated mice." (PMID 33608025, 2021). "Previous studies confirmed that ICAM-1 was related to the development of multi-organ failure, and the persistent increase of ICAM-1 in plasma of sepsis-induced multi-organ failure may indicate a proinflammatory endothelium phenotype." (PMID 33330617, 2020). "In addition, nutlin-3a significantly decreased IL-6, VEGF, ICAM-1, and CK levels in serum (p < 0.05) and IL-6 and VEGF levels in the liver of mice with sepsis (p < 0.05)." (PMID 31480519, 2019). "In emergency department patients with sepsis, resistin and NGAL correlated with the expression of the endothelial cell adhesion molecules (VCAM-1, ICAM-1) and were associated with septic shock, but not with mortality." (PMID 30517161, 2018). "E-selectin and ICAM-1 expression increased in AK-7 vs. vehicle treated mice, supporting a role for SIRT-2 in repressing inflammatory reactions in microvasculature during obesity with sepsis." (PMID 27500833, 2016). "It was found that recombinant β-defensin-2 could downregulate the expression of ICAM-1 in lung tissue 24 h, 36 h, and 72 h after CLP and significantly raised the 7-day survival rate in sepsis mice." (PMID 25210703, 2014).
Sepsis (continued). "We have previously shown that ICAM-1 and E-selectin, two of the most commonly used markers of endothelial activation in sepsis, do not correlate with endothelial function as measured by RH-PAT." (PMID 20482750, 2010). "P- and E-selectin, ICAM-1 and VCAM-1 all undergo proteolytic cleavage of the extracellular region of the membrane-bound receptor and levels of these soluble forms are increased in experimental and clinical sepsis." (PMID 20942957, 2010). "The analysis included age, gender, SAPS II score, presence or absence of sepsis and each of the biomarkers that showed significant differences between groups in bivariate analyses: IL-8, ICAM-1, protein C, PAI-1 and thrombomodulin." (PMID 18358078, 2008). "To further determine whether 6 key target genes identified in this study (AKT1, MMP9, ICAM1, TLR4, BCL2, and HIF1A) could be used as therapeutic targets for sepsis and COVID-19, we downloaded the gene expression profiles of sepsis and COVID-19 patients from the GEO database (GSE95233, GSE171110)." (PMID 41411324, 2025). "In contrast, the expression of genes governing immune‐promoting function of neutrophils was decreased or had no significant change, except for ICAM1, which displayed an increased expression in sepsis patients but a smaller change compared with suppressive signature genes." (PMID 39887584, 2025). "CSF concentrations of soluble ICAM-1 were increased only in PWH with neurological diseases, probably because of a passive flow from blood through an impaired BBB; similarly, CSF-soluble forms of adhesion molecules also increased in course of sepsis, CNS inflammation, such as meningitis and dementia." (PMID 38704619, 2024). "In this study, the protein levels of vascular cell adhesion molecule 1 (VCAM1) and intercellular adhesion molecule 1 (ICAM1) in the lung tissue of DEFA1/DEFA3-HCN mice were significantly higher than those of DEFA1/DEFA3-LCN mice and WT mice 24 hours after the onset of disease septicemia." (PMID 36776394, 2022). "However, the role of Mid1 in regulating endothelial cell expression of ICAM-1 and neutrophil adhesion during sepsis has not been investigated." (PMID 36614145, 2022). "The AUCs of Urokinase, ICAM-1, VEGFR2, and combined scores were 0.650, 0.688, 0.643, and 0.741, respectively, indicating that Urokinase, ICAM-1, VEGFR2 could be the helpful factors for diagnosis in patients with sepsis." (PMID 35363162, 2022). "A similar phenotype was observed in a model of sepsis, where whole-body PTP1B deletion not only improved survival rate in response to septic shock, but decreased cardiac dysfunction and the expression of pro-inflammatory markers such as IL1β, ICAM-1, VCAM-1, COX-2 and iNOS." (PMID 28899902, 2017). "During sepsis, this imbalance could contribute to alteration of microvascular tone and integrity, as well as the activation of cell adhesion molecules, such as VCAM-1 and ICAM-1." (PMID 28333102, 2017). "Therefore, miR-23b may play a significant role in the pathogenesis and progression of sepsis by inhibiting the expression of inflammatory factors, including NF-κB, TNF-α, IL-6, ICAM-1, E-selectin and VCAM-1." (PMID 25780398, 2015). "ICAM-1, VCAM-1 and E-selectin are important cell adhesion factors that regulate the activity of inflammatory and vascular endothelial cells, pro- and anti-inflammatory factors, as well as inflammatory cell migration to tissues and organs; thus, these factors play an important role in sepsis." (PMID 25780398, 2015). "Notably, within the PPI network analysis, key proteins including ICAM1, Resistin, TIMP1, VWF, CRP, and HMGB1 were identified at the central nodes of the network module, revealing a significant difference (P < 0.05) between the normal group and the sepsis group." (PMID 38951753, 2024).